SFRP2 (secreted frizzled related protein 2)
Diseases named in the same sentence as SFRP2 in open-access papers (continued):
Sharing a sentence is not in itself a finding about the gene and the disease.
breast carcinoma (continued). "Our approach was to investigate SFRP2 expression and promoter methylation in breast cell lines, primary breast carcinomas and normal breast tissues, followed by comprehensive statistical correlation analysis with clinicopathological factors and patient survival." (PMID 18990230, 2008). "In addition, SFRP2 overexpression in a human breast cancer cell line (MCF7) inhibited apoptosis following UV light exposure, while increasing cell-substrate adhesion capacity." (PMID 18990230, 2008). "In order to answer the question whether SFRP2 promoter methylation occurs in primary breast carcinoma as well we analyzed 199 mammary tumor samples by MSP." (PMID 18990230, 2008). "In breast cancer, several genes encoding inhibitors of canonical Wnt/β-catenin signalling have been reported to be frequently hypermethylated, for example, SFRP1, SFRP2, SFRP5, WIF1 and DKK1." (PMID 18826564, 2008). "Additionally, in a commercially available cDNA of human normal breast tissue (Clontech, Heidelberg, Germany) SFRP2 was strongly expressed while its expression was substantially reduced in Clontech's cDNA of primary breast carcinoma." (PMID 18990230, 2008). "However, SFRP2 expression analyses in normal and breast carcinoma tissues as well as patient survival analysis in relation to SFRP2 methylation were not addressed." (PMID 18990230, 2008). "The high incidence and the putative specificity of this epimutation may qualify SFRP2 methylation as potential candidate in a screening marker panel for the early detection of human breast cancer." (PMID 18990230, 2008). "Contrasting the view that SFRP2 acts as a tumor suppressor gene, Lee and co-workers suggested that SFRP2 exhibits rather an oncogenic property in breast tissue since this group detected strong upregulation of SFRP2 protein in canine mammary tumors relative to normal canine breast tissues." (PMID 18990230, 2008). "How might stromal SFRP1 and SFRP2 facilitate breast cancer progression?" (PMID 37091166, 2023). "However, few studies have reported serum sFRP2 levels in breast cancer." (PMID 30944668, 2019). "In addition, we provide evidence that SFRP2 protein expression is commonly reduced in breast cancer and that SFRP2 methylation might be a potential biomarker useful for early detection of this disease." (PMID 18990230, 2008). "Nevertheless, SFRP2 methylation may be potentially useful as a molecular tumor biomarker in a DNA methylation biomarker based screening assay, as it may display high clinical sensitivity and specificity in detecting breast cancer cells." (PMID 18990230, 2008). "The analysis conducted through Gepia 2.0 further demonstrated the expression of SFRP2 and LPL in different breast cancer subtype groups." (PMID 38791477, 2024). "The result also showed that downregulated genes SFRP2 and LPL were positively correlated in all breast cancer subtype groups." (PMID 38791477, 2024). "Our independent analysis of primary ER+PIK3CA-mutant breast cancers, which exhibit high INPP4B expression, identified these and additional upregulated Wnt genes (LEF1, MYCN, FZD7, SFRP2, TCF7L1, CTNNB1, FZD4, and SFRP1)." (PMID 34035258, 2021). "Epigenetic silencing of WNT/β‐CATENIN antagonists is frequently observed in breast cancer, and reduced expression of APC, CDH1, SFRP1 and SFRP2 due to promoter hypermethylation has been reported in many breast tumours." (PMID 33462997, 2021). "Several Wnt/β-catenin antagonists were epigenetically repressed in breast cancer, including WIF1, SFRP1, SFRP2, SFRP5, DKK1, and DKK3." (PMID 28467796, 2017). "Seven over-expressed breast cancer genes, namely BCAR1, HSD17B1, MMP14, PLAU, SFRP2, SPP1 and VCAN, had increased promoter methylation and their promoters contained the tumor-specific hypermethylated A-6 or A-7 HMRs." (PMID 25706888, 2015). "We initially assessed promoter methylation of SFRP1, SFRP2, SFRP5, ITIH5, DKK3, and WIF1 in 112 paired breast cancer tissue and serum samples by using qualitative MSP." (PMID 23320751, 2013).
breast carcinoma (continued). "In the present study, seven potential breast cancer marker candidates (SFRP1, SFRP2, SFRP5, WIF1, DKK3, ITIH5, and RASSF1A) were studied with regard to early breast cancer detection in serum." (PMID 23320751, 2013). "For that reason, in the present study we initially evaluated the expression status of SFRP1, SFRP2 and SFRP5 in a panel of breast cancer cell lines." (PMID 18283316, 2008). "As such, the reduced levels of stromal SFRP1 and SFRP2 in DCIS and IDC may facilitate WNT signaling and promote breast cancer growth, survival, invasion, or stem cell activity." (PMID 37091166, 2023). "Serum SFRP2 has been shown to be elevated in patients with breast cancer compared to patients without cancer." (PMID 34070758, 2021). "Furthermore, we tested the expression of FZD2, SFRP2, STK31, and LALBA proteins in canine mammary (CF41 and P114) and human breast cancer cells lines (HCC1500, T47D, DCIS.com, MDA231, and MCF7)." (PMID 32053966, 2020). "In addition, we found that SFRP2 and SFRP5 are methylated in both cultured breast cancer cells and primary breast cancers at quite high frequencies." (PMID 18283316, 2008). "We also examined the expression of these genes in a separate cohort of 698 luminal (ER/PR+) breast cancers using the TCGA dataset, where PIK3CA-mutant cancers displayed significantly higher expression of eight Wnt genes (LEF1, TCF7L1, TCF7L2, CTNNB1, LRP6, SFRP2, WNT5A, and MSX2)." (PMID 34035258, 2021). "Importantly, SFRP2 methylation was independent of relevant clinicopathological factors, thus being unlikely related to disease stage or a molecular breast cancer subtype." (PMID 18990230, 2008). "However, to the best of our knowledge, serum sFRP2 has not yet been reported in breast cancer." (PMID 30944668, 2019).
colorectal cancer (42 papers, 2008 to 2026). A primary or metastatic malignant neoplasm that affects the colon or rectum. "Methylation of the VIM and SEPT9 genes had good diagnostic efficacy for colorectal cancer, while hypermethylation of the SFRP2 gene is an early diagnostic feature of colorectal cancer." (PMID 38814387, 2025). "Abnormal methylation of secreted frizzled-related proteins (SFRPs), specifically SFRP2, has been associated with cancer risk, especially in hepatocellular and colorectal carcinoma." (PMID 39859530, 2025). "Hypermethylation of SFRP2 has previously been associated with the development of colorectal cancer, gastric cancer, and pancreatic cancer." (PMID 29212200, 2017). "SFRP2 is also downregulated in colorectal cancer and is linked with the EMT as well as proliferation." (PMID 26822534, 2016). "Aberrant promoter methylation of SFRP2 is associated with poor survival of colorectal cancer." (PMID 33030559, 2021). "Our data suggest that SFRP2 methylation (and loss expression of SFRP2) may be a potential candidate in the insulin sensitivity and colorectal cancer axis." (PMID 32517740, 2020). "In addition, to test whether the hyper-methylation of SFRP2 promoter is functionally associated with a down-regulated expression of SFRP2 at the transcriptomic level, we performed in vitro demethylation assays, using different colorectal carcinoma cell lines." (PMID 31319558, 2019). "Because the downregulation of SFRP2 is a marker of colorectal cancer, this pattern agrees with known role of immunoglobulin-expressing cells in infiltrating and combating the tumor." (PMID 38168288, 2024). "Several studies have suggested secreted frizzled-related protein 2 (SFRP2) gene as a potential clinical biomarker in colorectal cancer (CRC)." (PMID 38802858, 2024). "In colorectal cancer, upregulation of the SOX2 gene in colonic stromal cells induces SFRP2 overexpression in cancer-associated fibroblasts, thereby promoting tumor formation." (PMID 39850884, 2024). "Zhang and his colleagues in their meta-analysis showed that SFRP2 methylation serves as a promising marker with a great potential in early colorectal cancer diagnosis." (PMID 30024936, 2018). "Methylation changes in the promoter region of SFRP2 have been proposed as a potential noninvasive biomarker for colorectal cancer." (PMID 30545422, 2018). "Sfrp2 is another Wnt suppressor that is down-regulated by promoter methylation in colorectal cancer." (PMID 29254234, 2017). "Results suggest a gradual expansion of methylation across CpG islands in MGMT, RASSF2, and SFRP2 promoters during colorectal cancer progression and highlighted their potential role as biomarkers for diagnosis and disease prediction for specific cancer types." (PMID 27095449, 2016). "Overall, the effects of SFRP2 overexpression in HCT116 cells suggest that this protein may have a tumor-suppressive function in colorectal cancer." (PMID 38802858, 2024). "Downregulation of SFRP2 expression promotes colorectal cancer cell proliferation." (PMID 38168288, 2024). "Secreted frizzled‐related protein type 2 (SFRP2) is a potential epigenetic biomarker of colorectal cancer, which could inhibit Wnt signaling." (PMID 38405061, 2024). "Furthermore, we aimed to evaluate the effect of recombinant human SFRP2 in colorectal cancer cell model (HCT116 cells) to understand its contribution to colorectal carcinogenesis, and to recommend new strategies for its use as a cancer biomarker." (PMID 38802858, 2024). "Indeed, the Wnt/β-catenin pathway is constitutively active in most colorectal cancers, where the loss of function mutation and/or epigenetic silencing of negative regulators like APC, AXIN2, DKK1, or SFRP2 are common facts." (PMID 34063173, 2021). "Finally, we tested the effect of vitamin D on the SFRP2 methylation in human colorectal carcinoma cell lines 116 (HCT116) and studied the association of neoadjuvant therapy under the 30th percentile vitamin D with SFRP2 promoter methylation." (PMID 32517740, 2020).
colorectal cancer (continued). "Meanwhile, sFRP2 is downregulated by epigenetic promoter hypermethylation in gastric cancer, colorectal cancer, melanoma, and oral squamous cell carcinoma, suggesting that sFRP2 could be regarded as a tumor suppressor." (PMID 30944668, 2019). "However, despite measuring the SFRP2 gene expression in three different human colorectal carcinoma cell lines (HCT116, LoVo, and Caco-2), we only observed expression recovery of SFRP2 in HCT116, after the AZA treatment." (PMID 31319558, 2019). "Furthermore, miR-224 expression is upregulated in colorectal cancer tumor samples and is inversely correlated with GSK3β and SFRP2." (PMID 26822534, 2016). "Also, restoring the expression of GSK3β and SFRP2 restrained miR-224-induced aggressive phenotype of colorectal cancer cells." (PMID 26822534, 2016). "In contrast, in faecal DNA SFRP2 methylation was proven to be a highly promising screening marker for colorectal cancer, even potent to detect early lesions like adenoma, aberrant crypt foci and colorectal polyps due to the absence of SFRP2 methylation in normal colonic mucosa." (PMID 18990230, 2008). "BMI could influence the DNAm level of SFRP2 in patients with colorectal cancer." (PMID 38405061, 2024). "At the same time, SFRP2 methylation was found to occur high-frequent in colon cancer (83–90%), which may have forced the establishment of SFRP2 methylation as a promising sensitive screening marker for the stool-based detection of colorectal cancer and premalignant lesions." (PMID 18990230, 2008). "Some DNA methylation biomarkers such as Septin9 (SEPT9), Secreted frizzled- related protein 2 (SFRP2), and Syndecan 2 (SDC2) from blood or stool have been considered as feasible biomarkers for early detection of colorectal cancer." (PMID 35754025, 2022). "SFRP1, SFRP2, and DKK2 were appropriate markers to differentiate colorectal cancer cells from normal crypt cells." (PMID 28533824, 2017). "Hypermethylation of SFRP2 that resulted in the downregulation of SFRP2 was detected via methylation-specific PCR (MSP) and quantitative PCR (qPCR) in colorectal carcinoma as compared to adenoma." (PMID 25997610, 2015). "Interestingly, we found that four of the markers best suited to distinguish cases from controls in our study were the already well-known colorectal cancer markers IKZF1, SFRP1, SFRP2 and VIM." (PMID 37438612, 2023). "In addition, our results suggest that SFRP1, SFRP2, and DKK2 markers can differentiate colorectal cancer cells from normal crypt cells." (PMID 28533824, 2017). "Colorectal cancer patients with hypermethylation of the secreted frizzled related protein 2 (SFRP2) gene in tumor tissue, stool and blood samples had a significantly lower overall survival than those with negative results for SFRP2 methylation analyses." (PMID 35055034, 2022). "Finally, expression analyses of miR-224, GSK3β and SFRP2 in 20 clinical colorectal cancer tissues revealed significant negative correlations between miR-224 and the expression of GSK3β and SFRP2." (PMID 26822534, 2016). "Quantitative methylation-specific PCR (qMSP) was used to evaluate methylation of four Wnt-antagonists, SFRP2, WIF-1, DKK3 and SOX17 in 18 normal colorectal mucosa samples, 9 colorectal cancer cell lines, 18 carcinomas, 44 nonpolypoid and 44 polypoid adenomas." (PMID 24350795, 2013).
gastric cancer (30 papers, 2007 to 2026). A primary or metastatic malignant neoplasm involving the stomach. "It should be noted, though, that down regulation of sFRP-1 predisposes the mammary gland to tumorigenesis while sFRP-2 is significantly downregulated in gastric cancer, and downregulation of both sFRP-1 and sFRP-2 contributes to cervical cancer progression." (PMID 20948575, 2010). "The detection of SFRP2 methylated DNA in serum samples of gastric cancer patients further implies their potential diagnostic value in gastric cancer." (PMID 17848950, 2007). "The high detection rate of methylated SFRP2 in serum indicates that SFRP2 methylation has its diagnostic and therapeutic values in gastric cancer." (PMID 17848950, 2007). "Studies with larger sample size are necessary to discern the early diagnostic and prognostic significance of detecting SFRP2 methylation in the serum of gastric cancer patients with different subtypes." (PMID 17848950, 2007). "Thus, SFRP2 methylation also plays a crucial role in gastric cancer development, and its hypermethylation is closely associated with low expression." (PMID 39729237, 2025). "Our study confirmed the diagnostic value of RNF180 and SFRP2 in GC, indicating that their combination can serve as a biomarker, enhancing the accuracy of gastric cancer diagnosis." (PMID 39541711, 2024). "WIF1 and DKK3 to poor prognosis in breast cancer; FGR3 mutation and hypermethylation to bladder cancer and SFRP2 hypermethylation to gastric cancer (GC)." (PMID 27050149, 2016). "In gastric cancer, SFRP2 expression is significantly lower in tumor tissues compared to adjacent non-cancerous tissues." (PMID 39729237, 2025). "Stimulating SFRP2 expression in gastric cancer can inhibit tumor cell proliferation and induce apoptosis." (PMID 39729237, 2025). "In this study, we explored a previously neglected aspect by comprehensively investigating the potential of combining RNF180 with SFRP2 for gastric cancer diagnosis." (PMID 39541711, 2024). "It has been shown that RNF180 and SFRP2 are hypermethylated in gastric cancer, and our study supports this finding." (PMID 39541711, 2024). "Future studies should further explore the combination of RNF180 and SFRP2 with traditional tumor markers or other biomarkers to enhance the accuracy of gastric cancer diagnosis." (PMID 39541711, 2024). "Although the methylation detection of RNF180 and SFRP2 shows potential for diagnosing gastric cancer, further technical optimization is necessary to ensure the reproducibility and stability of the assay." (PMID 39541711, 2024). "We screened eight DDR-related genes (ZBTB7A, POLQ, CHEK1, NPDC1, RAMP1, AXIN2, SFRP2, and APOD) to establish a risk model, which can predict the prognosis of gastric cancer patients and guide the clinical implementation of immunotherapy." (PMID 36578802, 2022). "In gastric cancer, SFRP2 is downregulated in gastric cancer tissues, while forced SFRP2 expression suppresses proliferation and tumor growth of gastric cancer cells." (PMID 34852024, 2021). "Promoter methylation of RNF180, DAPK1 and SFRP2 can be detected in plasma DNA of patients with gastric cancer." (PMID 28418867, 2017). "The downregulated expression of SFRP2 has been shown to correlate with promoter hypermethylation in 73.3% of cases of primary gastric cancer." (PMID 25997695, 2015). "Among the four SFRPs with CpG islands in the promoter region, we found that only SFRP2 was silenced and methylated in gastric cancer." (PMID 17848950, 2007). "Promoter hypermethylation of SFRP2 was detected in 73.3% primary gastric cancer tissues, 37.5% of samples showing intestinal metaplasia and 20% adjacent normal gastric tissues." (PMID 17848950, 2007). "For SFRP2, 22 (73.3%) gastric cancer specimens had SFRP2 methylation, which was significantly higher than that of adjacent non-cancer tissue (20%, P<0.0001)." (PMID 17848950, 2007).